CDKN1A (cyclin dependent kinase inhibitor 1A)
Diseases named in the same sentence as CDKN1A in open-access papers (continued):
Sharing a sentence is not in itself a finding about the gene and the disease.
tumor (continued). "Beyond CDKN1A and TP53INP1, ACER2 also plays a critical role in the DNA damage response and multiple lines of evidence support its role as a tumor suppressor in cancer cells." (PMID 41345520, 2025). "It promotes tumor progression by directly suppressing phosphatase and tensin homolog (PTEN) and cyclin-dependent kinase inhibitor 1A (CDKN1A), thereby enhancing c-Met/PI3K/Akt signaling." (PMID 40943288, 2025). "FBXW7 was the most recurrently observed F-box protein among K562 hits, paired with many cell cycle related proteins (e.g. CDK2AP1, CDK4, CDKN1A, CKS1B), consistent with the known role of FBXW7 as a tumor suppressor." (PMID 39919746, 2025). "We compared the expression levels of the CD99, CDKN1A, NES, SOX2, and TUBB3 genes in ES tumor samples and controls consisting of normal muscle tissue." (PMID 38785514, 2024). "CDKN1A and PCNA inhibit the transition from the G1 to the S phase of the cell cycle, thus blocking cancer cell division and tumor growth." (PMID 39339270, 2024). "Our gene expression analysis indicates a reduction in the transcription of CD99 and CDKN1A and increased levels of SOX2 in ES tumors, the latter being consistent with the role of stemness in tumor progression." (PMID 38785514, 2024). "Among that, the protein expression of IGF2BP3, B2M, CD36, CDKN1A, ANKRD33B, and LHFPL2 were up-regulated; However, the protein expression of APP and CTDSPL was low in both normal and tumor tissues." (PMID 39470474, 2024). "The results show that BRAF, CDKN1A, DIABLO, PEA15, ERRFI1, and RPS6KB1 are highly expressed in tumor cell lines, which is the same as in the TCGA database." (PMID 39239554, 2024). "Our findings revealed significant correlations between AURKA, CDKN1A, and STEAP3 and tumor exclusion." (PMID 37608887, 2023). "Further work is needed to understand the expression patterns of RASSF6 and PTPRG, which are generally considered to be tumor suppressors and genes like BIRC3 and CDKN1A that are known to be involved in a number of different cancers." (PMID 37910143, 2023). "The RT-qPCR assay results illustrated that both CD81 and CDKN1A were significantly downregulated in the tumor tissue compared adjacent normal tissue (p < 0.0001 of CD81 and p = 0.0029 of CDKN1A)." (PMID 37051592, 2023). "CDKN1A and CDKN2B exert an important tumor-suppressive function by regulating cell cycle progression." (PMID 37932451, 2023). "Consequently, it has been suggested that CDKN1A may exert an influence on tumor genesis." (PMID 37730565, 2023). "CDKN1A showed low expression levels in TBX1-positive K-562 and TK-6 cells, supporting its tumor suppressor status in this disease." (PMID 38203204, 2023).
tumor (continued). "We also analysed TCGA COAD data, including mRNA expression data for 459 tumour and 41 normal samples and miRNA expression data for 272 tumour and eight normal samples (version 2016_01_28) for SRSF3‐miR‐17/20a‐CDKN1A expression signature." (PMID 37306233, 2023). "In line with this, the overexpression of genes related to the cell cycle seems to be the principal anti-tumor activity of propolis because both treated A4gnt KO mice and wildtype C57BL/6J mice showed increased upregulation of CDKN1A." (PMID 36673507, 2023). "In this study, genes including THBS1, CDKN1A, FBN1, TGFB1, and IGFBP3 were found to be downregulated in tumor cell lines." (PMID 35340229, 2022). "We included Cdkn1a in this analysis because Cdkn1a is a well-documented HEB and E2A target gene and because of strong genetic evidence for Cdkn1a tumor suppressor function in mice harboring one additional Cdkn1a allele." (PMID 35401501, 2022). "Taken together, our findings revealed that IGF2-AS was a tumor-suppressor, and inhibited tumorigenesis and aggressive behaviors of HCC cells via sponging miR-520h to up-regulate CDKN1A both in vitro and in vivo." (PMID 34516353, 2021). "The increased expression of the CDKN1A gene in HNSCC has been correlated with nodal metastases, tumor recurrence, and decreased survival." (PMID 33718274, 2021). "The downregulation of IRF9 and VCAN expression was conserved until tumor excision, STAT1, and CDKN1A expression showed decreased tendency and STAT2, and PCNA expression were significantly reduced in the IRF9-knockdown group." (PMID 33430083, 2021). "It is already known that CDKN1A, BAX, CASP9 and E-cadherine are involved in tumor growth suppression and apoptosis." (PMID 34281228, 2021). "TFAP2C upregulates the GPX4 gene in tumor cells and regulates some ferroptosis regulators, such as epidermal growth factor receptor (EGFR), CDKN1A, and YAP1, thereby negatively regulating ferroptosis." (PMID 34804126, 2021). "The p21cip1, also known as cyclin-dependent kinase inhibitor 1 (CDKN1A), has been identified as a regulator of cell cycle and a tumor suppressor in multiple kinds of cancers." (PMID 32850410, 2020). "In tumor tissues, the ORs of both TREXes and NCTFs and CDKN2A and CDKN1A increased with the younger age quartile." (PMID 32859952, 2020). "Here, we found a new antiviral gene, CDKN1A, downstream of the RAS pathway to suppress the replication and oncolytic effect of M1 virus, and it has been reported to be a tumor suppressor." (PMID 33037696, 2020).
tumor (continued). "The Cip/Kip family members, CDKN1A and CDKN1B, can arrest cell proliferation and were initially considered as tumor suppressors." (PMID 32899752, 2020). "The silencing of CCAT1 in colon cancer cells reduces proliferation through CDKN1A/p21-mediated cell-cycle arrest in G1 phase and the injection of CCAT1 KD tumor cells delays tumorigenesis in xenograft models." (PMID 33142861, 2020). "Accordingly, in MCF-7 TIE2tet cells, induction of the expression of TIE2 with Dox-induced a significant increase of the cyclin-dependent kinase (CDK) inhibitors CDKN1A (or P21CIP1) and CDKN1B (or P27KIP1), as previously reported in dormant tumor cells." (PMID 32260072, 2020). "The CDKN1A was less downregulated in more advanced and aggressive cancers as it is positively correlated with TNM stage, primary tumor extension, and histopathological grade, and tended to be upregulated in tumors with distant metastases present." (PMID 32630408, 2020). "We found that the expression of cell cycle-related tumor suppressor genes, CCND2 and CDKN1A, was increased after CCRT." (PMID 31097034, 2019). "In our previous study, we have shown that simultaneous inhibition of CDKN1A and telomerase by imetelstat (JNJ-63935937, also known as GRN163L) leads to synergistic tumor growth inhibition." (PMID 29986697, 2018). "It has been also demonstrated that the normal function of this tumor suppressor miRNA is to down-regulate a number of putative oncogenes including validated miR-22 targets MAX, MYCBP, HDAC4, HDAC6, CDK6, CDKN1A and NCoA1." (PMID 29716630, 2018). "Recent findings in cancer research point to a role of this seed sequence in reinforcing the proliferative cellular program in a wide range of cancers, by repressing tumor suppressor genes such as PTEN, RBL2, LATS2, or CDKN1A." (PMID 30713549, 2018). "CDKN1A and KLF2 have been identified as novel tumor suppressors involved in cancer cell proliferation, apoptosis, and invasion." (PMID 30367681, 2018). "CDKN1A, one of the genes regulated by SNHG1 in accordance with the RNA-Seq, is capable of exhibiting the role of tumor suppressor genes in different kinds of cancer." (PMID 29970899, 2018). "While both are HIF-1 target genes, CDKN1A stalls cell cycle progression and VEGFA promotes tumor angiogenesis." (PMID 30423844, 2018). "In tumor cells (TC), HDAC inhibition predominantly induces G1-S cell cycle arrest by increasing CDKN1A/p21 expression." (PMID 27894105, 2017). "In short, we first prove that JMJD5 is a tumor suppressor gene in HCC pathogenesis, and the epigenetic silencing of JMJD5 promotes HCC cell proliferation by directly down-regulating CDKN1A transcription." (PMID 26760772, 2016). "We confirmed that miR-93 directly bound with the 3′ untranslated regions of the tumor-suppressor genes PTEN and CDKN1A, respectively,and inhibited their expression." (PMID 25633810, 2015).
tumor (continued). "Here, we show that LKB1 tumor suppressor is a DNA damage sensor, and together with its downstream kinase NUAK1, contributes to UVB-induced CDKN1A degradation, allowing DNA repair and genomic integrity." (PMID 25329316, 2014). "One of the genes that were induced by both EVI1 and etoposide was CDKN1A/p21/WAF, which in addition to its function as a cell cycle regulator plays an important role in conferring chemotherapy resistance in various tumor types." (PMID 23457546, 2013). "Molecular silencing of HDAC1 using small interfering RNA (siRNA) attenuated VPA-mediated regulation of CDKN1A, CDKN1B and LC3-I/II, regression of tumor cell growth and induction of autophagy." (PMID 23866964, 2013). "FOXP3 also induces expression of several tumor suppressors including p18 (CDKN2C), p21 (CDKN1A), LATS2, and ARHGAPS." (PMID 23341929, 2013). "Several common target genes in the networks were down-regulated in both wt and mt tumor cells, such as ITGA5 and S100A2 (adhesion and migration), SERPINE1 (angiogenesis), CDKN1A (growth arrest), and PLAU and SERPINE5 (proteolysis)." (PMID 24069219, 2013). "Some oncogenes and tumor suppressors with cancer-specific alternative splicing, such as EWSR1, CDKN1A, and GLTSCR2, are present in more types of cancer." (PMID 19266097, 2009). "Amongst these are notable tumor related genes AKT3, CDKN1A, ESR1, FOXO1, TSC2, ERBB3, and NRG4." (PMID 40522948, 2025). "Between ARGs_Low tumour cells and T cells, ITGB1-CD46 and ITGB1-ENG were ligand-receptor pairs with strong regulatory potential, while COL1A2, CCL3, SERPINE1, FN1 and CDKN1A were top genes target to TGFB1." (PMID 40830065, 2025). "Importantly, the differential expression of checkpoint regulators between MSI and MSS tumors remained significant after adjusting for tumor site, highlighting MSI status as an independent determinant of CDKN1A-mediated 5FU sensitivity." (PMID 41440189, 2025). "Furthermore, miR-93-5p bound directly to the 3′ untranslated regions of tumor-suppressor genes PTEN and CDKN1A, inhibiting their expression and resulting in enhanced activity of the c-Met/PI3K/Akt pathway." (PMID 39677943, 2024). "To investigate the efficiency of tumor-specific MRCP regulating endogenous gene expression in tumor cells for inhibiting the malignant phenotype, we constructed and evaluated MRCP to regulate cyclin-dependent kinase inhibitor 1A (CDKN1A) and Bax expression in tumor cells." (PMID 39507755, 2024). "Of note, we can use cells, such as immortalised cell lines or tumour-derived cell lines, from these mice to perform CRISPR screens to search for positive and negative regulators of the expression of the Cdkn1a/p21 and Bbc3/Puma genes and the pathways in which they function." (PMID 39160273, 2024). "CDKN3 is a relatively unique member of the CDKN family because overexpression of CDKN3 has been proven to be oncogenic in multiple cancer types 41, unlike the tumor suppressive CDKNs, such as CDKN1A and CDKN1B." (PMID 38356706, 2024).
tumor (continued). "In order to investigate the function of CDKN1A in radioresistance in more detail, we used A549 cells with or without CDKN1A overexpression to create a subcutaneous tumor model in nude mice." (PMID 38468925, 2024). "As expected, the MRCP can activate the CDKN1A expression in tumor cells significantly, while not in normal cells." (PMID 39507755, 2024). "Notably, both CDKN1A and CDKN2A belong to the same family (cyclin dependent kinase inhibitor) and show the same change trend in the tumor development stage while with different trends in the development stage." (PMID 38070141, 2023). "In mouse models, the deletion of CDKN1A/p21 does not affect carcinogenesis until around 16 months, where spontaneous tumours are observed." (PMID 38139316, 2023). "We suggested that STARD14 may achieve the regulation of ferroptosis in LUAD by promoting the expression of CDKN1A and FANCD2, ultimately contributing to tumor progression." (PMID 37790851, 2023). "Thus, a key tumor suppression mechanism of SOCS1 is to prevent the tumor suppressors SOCS3 and CDKN1A from gaining oncogenic potential." (PMID 36765862, 2023). "For instance, the cyclin-dependent kinase inhibitors (CDKs), CDKN1A (p21Cip1), CDKN1B (p27Kip1), and CDKN2A (p16Ink4A), reprimo (RPRM), stratifin (SFN), and CDK1 are all frequently hypermethylated and play various roles in tumor radioresistance." (PMID 37455903, 2023). "Mice lacking CDKN1A alone (Socs1fl/flCdkn1a−/−) also showed an increased incidence and tumor volume, supporting the tumor suppressor function of CDKN1A in the liver." (PMID 36765862, 2023). "In addition, gene co-expression analysis using TCGA OV tumor dataset with GEPIA2 indicated that the expression level of ERβ positively correlated with FDXR and CDKN1A." (PMID 35806169, 2022). "miR-149-3p could enhance proliferation and migration by targeting CDKN1A and TIMP2 in vitro, and promote tumor growth and weight in vivo." (PMID 34798882, 2021). "P21 (CDKN1A) and P27 (CDKN1B) are known as negative regulators that could induce cell cycle arrest at the G1/S phase and block tumor cell growth." (PMID 34869591, 2021). "Genetic deletion of Cdkn1a or Cdkn1b does not result in major developmental or proliferation defects but results in spontaneous tumor formation in some tissues of adult mice." (PMID 33078209, 2021). "In addition, siRNA experiments showed that VCAN diminished the tumor promoting effects of IRF9 and indicated the involvement of the tumor suppressor CDKN1A." (PMID 33430083, 2021). "The authors performed an RNA transcriptome comparison between SNHG1 knockout and control cells and found differential expression of hundreds of transcripts, including the established tumor suppressor and EZH2 target CDKN1A, which showed significant upregulation upon SNHG1 knockout." (PMID 32331331, 2020). "TP53INP1, CDKN1A and TIMP2 are able to regulate the proliferation and growth of tumor cells." (PMID 32612456, 2020).